G6PD (glucose-6-phosphate dehydrogenase)
Diseases named in the same sentence as G6PD in open-access papers (continued):
Sharing a sentence is not in itself a finding about the gene and the disease.
vivax malaria (continued). "7-day high dose primaquine (total dose of 7 mg/kg) is as efficacious as standard 14-day high-dose primaquine in radical treatment of vivax malaria at 1 year follow-up, but quantitative G6PD testing is required as there is a higher risk of haemolysis in treatments with a higher daily primaquine dose." (PMID 31900172, 2020). "Primaquine (PQ) prevents relapses of vivax malaria but may induce severe haemolysis in glucose-6-phosphate dehydrogenase (G6PD) deficient patients." (PMID 30940140, 2019). "G6PD deficiency has implications for the safe treatment for Plasmodium vivax malaria." (PMID 30184203, 2019). "It appears that the problem of G6PD deficiency excludes many people from safe and effective treatment at the latent stage of vivax malaria, such as the G6PD-deficient persons, pregnant and lactating women, young infants, people with chronic hepatic problems, and a few others." (PMID 30286752, 2018). "Here, we conduct the first ever ex vivo experiments to determine whether the G6PD-Mahidol mutation (487G>A) in hemizygous and homozygous status poses a barrier to the invasion and the normal development of vivax malaria parasites." (PMID 28591790, 2017). "Similarly, G6PD Mediterranean (G6PD-Med)—a variant common in Asian countries confers immunity against vivax malaria in hemizygous males." (PMID 29065882, 2017). "Therefore, quantitative analysis of the G6PD activity is required to determine the safety of primaquine administration for radical cure of vivax malaria in people carrying these G6PD deficient variants." (PMID 26226515, 2015). "The relatively lengthy course of primaquine treatment required for radical cure of vivax malaria might be a major safety challenge for G6PD deficient people." (PMID 26226515, 2015). "This study, however, shows that the probability of individuals with vivax malaria being deficient for G6PD may be significantly lower than in the general population from which they are drawn." (PMID 20520804, 2010). "While the application of these results to other settings may vary due to differences in costs and the epidemiology of vivax malaria and G6PD deficiency, the robustness of these findings should be reassuring, particularly where healthcare facilities expect to see a large number of patients annually." (PMID 40978565, 2025). "Given the paucity of hypnozoitocidal candidates and narrow safety profiles with TQ, the radical cure activity of T111 is promising, whether on its own or as a synergistic partner to improve the TQ therapeutic window for treatment and prevention of vivax malaria, including in G6PD deficient patients." (PMID 40678217, 2025). "However, a case–control study from Northern Myanmar in a population with a high prevalence (25.2%) of the G6PD Mahidol variant gave adjusted odds ratios for having acute vivax malaria of 0.213 (95% CI, 0.093–0.487) for male 487A hemizygotes, and 0.248 (0.110–0.561) for female heterozygotes." (PMID 33543710, 2021). "A recent trial of this regimen in vivax malaria patients with the more severe Viangchan G6PDd variant from Cambodia showed a greater fall in haemoglobin and a delayed recovery from anaemia in G6PDd compared to G6PD normal patients with one patient requiring a blood transfusion." (PMID 28155819, 2017). "In this study the prevalence rate of G6PD enzymatic activity was evaluated and the G6PD genetic variant identified in apparently healthy individuals from northeastern and southeastern regions of Venezuela to assess the rate and genetic basis of G6PD deficiency in endemic areas of vivax malaria." (PMID 26753754, 2016). "G6PD deficiency (Mediterranean type) conferred significant protection against vivax malaria infection in this population whether measured by phenotype or genotype, indicating a possible evolutionary role for vivax malaria in the selective retention of the G6PD deficiency trait in human populations." (PMID 20520804, 2010).
vivax malaria (continued). "The prescription of tafenoquine to those who test G6PD normal with a semi-quantitative test is a cost-effective strategy for the radical cure of vivax malaria in Brazil." (PMID 40978565, 2025). "The WHO recommends routine testing of G6PD activity to guide radical cure in patients with Plasmodium vivax malaria." (PMID 38687748, 2024). "93.9% (790/841) of eligible vivax malaria patients who successfully completed referral (429/434) and directly presented to the health center (360/407) were G6PD tested." (PMID 39028699, 2024). "Implementation research should be undertaken to assess the feasibility of G6PD testing patients before shorter course of primaquine or new single dose treatment being developed for radical cure of vivax malaria." (PMID 37072795, 2023). "A major consideration for a PoC community management of vivax malaria is the need for training, supervision, and monitoring of G6PD test use, and specifically supporting VMWs in G6PD categorization and corresponding treatment." (PMID 36986323, 2023). "For example, placing STANDARD G6PD at hospitals that see more vivax malaria patients will result in lower costs per test administered than placing them at community facilities where fewer patients are seen." (PMID 37242320, 2023). "In the future, VMWs can be resourced and trained to measure G6PD activity and provide vivax malaria treatment in the communities under supervision." (PMID 36986323, 2023). "Biosensors were provided to VMWs and health centre-based lab technicians after training to perform G6PD tests among vivax malaria and febrile patients over the period of a year." (PMID 36195916, 2022). "G6PD reference ranges in infants 2 to 6 months of age were established locally to support expansion of radical curative treatments of vivax malaria in lactating mothers, starting with clinical trials to quantify the amount of drug present in breast milk." (PMID 38406309, 2022). "Using DiaplexC G6PD genotyping kit (Asian type), they identified G6PD Mahidol and G6PD Viangchan with the frequency of 0.5% and 0.4% in vivax malaria patients (n = 545)." (PMID 36508454, 2022). "This cost-effectiveness analysis evaluated the use of the Standard G6PD quantitative screening test in vivax malaria treatment units in two municipalities of the Brazilian Amazon." (PMID 35324892, 2022). "Quantitative measurement of Glucose-6-Phosphate Dehydrogenase (G6PD) enzyme activity is critical to decide on appropriate treatment and provision of radical cure regimens for vivax malaria." (PMID 36195916, 2022). "Although VMWs have been involved in diagnosis of vivax malaria since 2021, much of their work is limited to diagnosing vivax malaria and then referring patients to health centres for G6PD measurement and radical cure therapy." (PMID 36195916, 2022). "Point-of-care glucose-6-phosphate dehydrogenase (G6PD) testing has the potential to make the use of radical treatment for vivax malaria safer and more effective." (PMID 34238299, 2021). "Unless there is very large population stratification within the Pashtun (confounding these results), the G6PD Med genotype confers a very large and gene-dose proportional protective effect against acute vivax malaria." (PMID 33543710, 2021). "The sheer sloppiness of the policies addressing G6PD testing has been a major barrier for countries facing an increasing relative proportion of vivax malaria." (PMID 33757538, 2021). "Overall, this study shows that the G6PD Mediterranean genotype confers a very large and gene-dose proportional protective effect against vivax malaria." (PMID 33543710, 2021). "Combined together they show clearly that G6PD Med provides a substantial gene dose proportionate protection against vivax malaria." (PMID 33543710, 2021). "vivax malaria, G6PD status, 8-aminoquinolines, and treatment restrictions linked to pregnancy and the post-partum period results in a sex related inequity." (PMID 32766454, 2020).
vivax malaria (continued). "The World Health Organization (WHO) recommends G6PD screening before providing primaquine as a radical treatment against vivax malaria." (PMID 32787970, 2020). "Adverse effects of vivax malaria in pregnancy, ineligibility of radical cure for pregnant and postpartum women, and difficulties in diagnosing intermediate levels of G6PD activity multiplied morbidity in this woman." (PMID 31969155, 2020). "The primary objective of this study was to evaluate the tolerability, safety, and efficacy of a 7-day high-dose (1 mg/kg per day) primaquine regimen for the radical cure of vivax malaria in patients screened as G6PD normal." (PMID 31327563, 2019). "Physicians dealing with imported cases of vivax malaria must strive to secure access to primaquine and to pre-empt relapses in their patients after having firmly established their G6PD status." (PMID 30497487, 2018). "Because the new national treatment scheme for vivax malaria allows the use of double dose in a shortened PQ treatment of 7 days, it is advisable to be alert for the possible cases of severe haemolysis that could occur especially among G6PD deficient males with a class II mutation." (PMID 30409136, 2018). "The widely recommended primaquine radical cure regimen for vivax malaria in G6PD-normal patients (0.25 mg/kg/day for 14 days; adult daily dose 15 mg) was based on experience in the Korean War (1950–1953) with long-incubation P. vivax." (PMID 29672516, 2018). "Both country programs plan to introduce or revise guidelines for safe, effective radical cure for vivax malaria with a routine G6PD testing." (PMID 30250397, 2018). "Prevalence of the G6PD was studied in 125 vivax malaria cases confirmed by laboratory and among 604 persons determined as negative by laboratory testing." (PMID 30286752, 2018). "Primaquine radical cure has the potential to transform, the control and elimination of vivax malaria but its safe delivery will require building appropriate capacity to test G6PD status." (PMID 28797255, 2017). "More than 80% of vivax malaria with predomination of G6PD Mediterranean type occurs in Southeast Asia." (PMID 28535765, 2017). "Among 532 soldiers, 219 had vivax malaria during the four months following repatriation to Java; 180 of these were otherwise healthy and G6PD-normal and enrolled in the trial." (PMID 26654101, 2015). "G6PD normal patients diagnosed with vivax malaria are randomized to receive either 7 or 14 days high dose primaquine or placebo." (PMID 26643116, 2015). "As with other treatments for vivax malaria, primaquine therapy should be administered in combination with AL when used to treat P. vivax infections, preferably after ascertainment of G6PD status." (PMID 22216359, 2011). "Thai adult males (N = 85) with acute Plasmodium vivax malaria and normal glucose-6-phosphate dehydrogenase screening were randomized to receive 30 mg or 60 mg primaquine daily for 7 days (N = 43 and 42, respectively)." (PMID 20348496, 2010). "Primaquine, at a low dose of 3.5mg/kg, has been recommended in the Cambodian National Treatment Guidelines since 2014 as a treatment for vivax malaria in patients with confirmed G6PD normal status, while deficient individuals were not to receive primaquine." (PMID 39028699, 2024). "However, there is an underlying need of mechanisms that bring treatment closer to patients reducing the need for referral, including equipping CHWs with G6PD tests to enable the provision of curative treatment of vivax malaria in the community." (PMID 39028699, 2024). "The parameters with the largest impact on the cost-effectiveness results across all municipalities were the lifetime and number of semiquantitative G6PD machines needed, severity and mortality due to vivax malaria, cost of G6PD test strips, and life expectancy." (PMID 38194420, 2024).
vivax malaria (continued). "The Duffy system and G6PD are polymorphic systems that offer great challenges to researchers not only due to their academic importance, but also due to their potential applications to treatment of vivax malaria." (PMID 35527254, 2022). "Based on the government treatment guidelines beginning from the first quarter of 2021, newly diagnosed vivax malaria patients seeking care from VMWs were offered a first dose of standard anti-malarials and were referred to the health centre for G6PD testing and radical cure treatment." (PMID 36195916, 2022). "An earlier retrospective study conducted in Afghan refugees in North-Western Pakistan suggested that G6PD Med hemizygotes were protected against vivax malaria, but there were too few observations to substantiate a trend to lower infection rates in female heterozygotes." (PMID 33543710, 2021). "The absence of G6PD testing leads to a familiar dilemma of having to weigh the risk of harm caused by relapsing vivax malaria versus potential haemolysis caused by 8-aminoquinolines." (PMID 33757538, 2021). "This shows that exclusion of anaemic patients in the first part of the study did not affect the interpretation of the protective effect of G6PD deficiency on vivax malaria." (PMID 33543710, 2021). "These are the only drugs providing radical cure of vivax malaria (prevention of relapse), but they are underused because G6PD deficiency testing is usually not available and prescribers are naturally concerned about precipitating dangerous haemolysis." (PMID 33543710, 2021). "Policymakers and stakeholders from 17 countries were interviewed starting with questions regarding the two fundamental aspects of vivax malaria treatment regimen, G6PD testing for routine treatment of vivax malaria and the radical cure regimens use in the country of the respondent." (PMID 33757538, 2021). "vivax malaria with 8-aminoquinolines is the limited availability of G6PD tests." (PMID 32766454, 2020). "For vivax malaria in the Americas, Asia, and Oceania, radical cure is widely recommended but is often not given because G6PD deficiency testing is unavailable." (PMID 29672516, 2018). "Primaquine is widely recommended for the radical cure of vivax malaria but it is often not given because testing for G6PD deficiency is not widely available outside large centres." (PMID 28155819, 2017). "The World Health Organization (WHO) recommends a total dose of 3.5–7 mg/kg primaquine divided over 14 days for the treatment of vivax malaria in those who are not deficient in the glucose-6-phosphate dehydrogenase (G6PD) enzyme." (PMID 28850568, 2017). "Therefore, deployment of primaquine for radical treatment of vivax malaria requires knowledge of the G6PD status in the patient populations." (PMID 26226515, 2015). "Neither G6PD deficiency nor any G6PD variant was found in individuals residing in vivax malaria endemic regions in the ROK." (PMID 24853873, 2014). "If successfully employed, routine G6PD testing could result in significant reductions in transmission of vivax malaria." (PMID 23834949, 2013). "A recent study demonstrated that one Asian variant (G6PD-Mahidol) was associated with lower levels of parasitaemia in Thai adults with vivax malaria, but not with P. vivax infection or with P. falciparum." (PMID 20520804, 2010). "However, an important challenge was the low referral rate (49.2%) of patients with vivax malaria from the community to the health center where G6PD testing and primaquine were provided; hence, a large proportion (62.9%) of eligible patients did not receive radical curative treatment." (PMID 39028699, 2024). "When G6PD testing is not available, it is frequently decided not to prescribe the drugs, despite their effectiveness in killing hypnozoites and preventing relapse, causing a significant burden for vivax malaria eradication." (PMID 36339627, 2022).
vivax malaria (continued). "Therefore, the profile of G6PD and CYP2D6 polymorphisms in this population should be characterized in order to provide information about the safety and efficacy of using 8-aminoquinolines in the treatment of vivax malaria." (PMID 36508454, 2022). "Hence, G6PD testing is recommended before radical treatment against vivax malaria." (PMID 33879156, 2021). "The alternative scenario of G6PD testing prior to prescribing unsupervised primaquine could increase healthcare provider costs by 42%, but decrease household costs by only 15%, while preventing 2.1 million cases of vivax malaria." (PMID 34061843, 2021). "The small but real risk of haemolysis in glucose-6-phosphate dehydrogenase (G6PD) deficient individuals after the administration of 8-aminoquinoline regimens is a major barrier to the uptake of radical curative regimens and slows the elimination of vivax malaria." (PMID 31888643, 2019). "However, the VHVs have generally engaged in blood-stage treatment of vivax malaria, and have not been allowed to prescribe PQ because of safety concerns about severe acute haemolytic anaemia in glucose-6-phosphate dehydrogenase (G6PD)-deficient patients." (PMID 30786891, 2019). "Nonetheless, in the meantime the present version of G6PD RDT certainly offers an option that is conspicuously better than the current standard of care for most patients with vivax malaria—no G6PD screening and the raw choices of risk of harm by the drug or by the parasite in withholding it." (PMID 26894297, 2016). "Patients (aged ≥6 months) with normal glucose-6-phosphate dehydrogenase (G6PD) and presenting with uncomplicated vivax malaria were enrolled." (PMID 31327563, 2019). "This study evaluated the cost-effectiveness of tafenoquine prescription to vivax malaria patients aged 16 years or older who test G6PD normal compared to primaquine with and without G6PD screening in Brazil from the SUS perspective." (PMID 40978565, 2025). "The generalisability of our findings is constrained to the large majority of vivax malaria patients with normal G6PD activity (≥30% G6PD activity or a negative qualitative test)." (PMID 39331646, 2024). "Some countries (e.g. Iran, Myanmar), which did not have G6PD testing available in endemic areas, have recommended the once weekly primaquine regimen as standard practice for all vivax malaria cases." (PMID 38319064, 2024). "Finally, there are no clinical data analyzed here; a future comprehensive study including such information would provide a better understanding of the implementation of G6PD and CYP2D6 testing on the use of 8-aminoquinolines for vivax malaria elimination." (PMID 36508454, 2022). "Our findings provide insights about genetic variations of G6PD and CYP2D6 in 88 vivax malaria patients from Yala, which may influence the safety and effectiveness of radical treatment." (PMID 36508454, 2022). "Further evidence of the persistent neglect of vivax malaria comes from the heterogeneity of treatment regimens and G6PD tests, not to mention their implementation and availability." (PMID 33757538, 2021). "In majority of the countries in the region (Afghanistan, Bangladesh, Bhutan, Cambodia, Indonesia, Pakistan, Solomon Islands and Papua New Guinea), G6PD tests were either not available or not mandatory for routine treatment of vivax malaria." (PMID 33757538, 2021). "The Ethiopian Federal Ministry of Health states that radical cure primaquine combined with chloroquine should be used to treat vivax malaria cases without prior G6PD testing." (PMID 33478414, 2021). "Nearly 85% of presentations with vivax malaria by the age of 5 years are recurrences as opposed to first episodes and G6PD status need only be assessed once." (PMID 31995581, 2020). "PQ treatment for radical cure in vivax malaria (0.25–0.5 mg/kg/day for 14 days) should not be given in individuals with G6PD activity below 30% of the adjusted male median (AMM)." (PMID 30314477, 2018).